PSMB10 (proteasome 20S subunit beta 10)
Diseases named in the same sentence as PSMB10 in open-access papers (continued):
Sharing a sentence is not in itself a finding about the gene and the disease.
type 1 diabetes (1 paper, 2023). "Moreover, we showed that PSMB10 is upregulated in a beta cell subset that is preferentially destroyed in the pancreases of individuals with type 1 diabetes." (PMID 37581620, 2023). "In addition, the selective upregulation of PSMB10 in a subset of vulnerable beta cells reinforces the relevance of our findings and points to a role of β2i in the processing and presentation of islet neoantigens to diabetogenic T cells in type 1 diabetes." (PMID 37581620, 2023).
urothelial carcinoma (1 paper, 2022). A malignant neoplasm derived from the transitional epithelium of the urinary tract (urinary bladder, ureter, urethra, or renal pelvis). "Our previous studies found a co-expression network associated with CD8+ T lymphocyte invasion in urothelial carcinoma, which contains PSMB8, PSMB9, PSMB10, PSME2, IRF1 and other genes." (PMID 36700205, 2022).
tumor (28 papers, 2014 to 2025). "In summary, our findings highlight that PSMB10 protein displays augmented expression levels in tumor tissues compared with normal tissues and is associated with unfavorable prognostic outcomes in patients." (PMID 38794205, 2024). "In our study, overexpression of PSMB10 mRNA and higher levels of proteins encoded by PSMB10 were found in ccRCC tissues compared to normal tissues, and was significantly related with patients' individual cancer stages and tumor grades." (PMID 35693739, 2022). "A pan-cancer analysis revealed that PSMB10 is significantly overexpressed in various tumor types compared to normal tissues, with notably high expression levels in KIRC." (PMID 38794205, 2024). "The heightened presence of PSMB10 within the tumor environment appears to be a significant factor in modifying cellular processes associated with KIRC, thereby highlighting its potential as a strategic target in treatment modalities." (PMID 38794205, 2024). "With respect to the within-group distribution, some genes have a narrow expression range (for example, KRT, HIF1A in both tumour and stromal compartments of p16+/HPV+ tumours, and PSMB10, B2M in the stromal compartment for all p16/HPV subgroups)." (PMID 39328208, 2024). "To start, we contrasted the immunohistochemical staining of BIRC5 (classical oncogene) and PSMB10 in primary tumor tissues and normal tissues in cases of KIRC." (PMID 38794205, 2024). "GBP5 and PSMB10 have been reported in tumors as part of the downstream interferon genes and are also considered to be the coordinators of tumor disease immunity." (PMID 34220795, 2021). "The IFN-gamma inducible genes (PSMB8/β5i, PSMB9/β1i, PSMB10/β2i), together with their chaperones have command of the tumor vulnerability to antigen-dependent killer cells." (PMID 34650125, 2021). "In contrast to these acknowledged functions to facilitate the immune clearance of tumor cells, we revealed here that the increased PSMB10 instead promotes AML cells to escape from CTL-killing both in vitro and in vivo through ubiquitinated degradation of MHC-I proteins." (PMID 40462177, 2025). "Interestingly, the 3 main immunoproteasome genes, PSMB8, PSMB9, and PSMB10, which digest cellular protein to antigenic peptides for antigen presentation, were also upregulated by VC in the WT tumor cells, as indicated by PSMB8 and others." (PMID 39388288, 2024). "This overexpression of PSMB10 in the tumor milieu might be contributing to the altered cellular processes in KIRC, suggesting its potential as a therapeutic target." (PMID 38794205, 2024). "Therefore, we believed that PSMB10 played a crucial role in the tumor development of RCC and could be identified as promising therapeutic targets of RCC." (PMID 35693739, 2022). "Meanwhile, our research has elucidated that PSMB10, a gene fundamentally involved in the ubiquitin-proteasome system, is markedly overexpressed in KIRC tumor tissues." (PMID 38794205, 2024). "The PD-1 expression scores of tumour cells and immune cells in patients with high expression levels of PSMB8, PSMB9, and PSMB10 were greater than low expression samples." (PMID 36700205, 2022). "PSMB8, PSMB9, PSMB10, PSME2, TAP1, and IRF1 promote CD8+ T cell infiltration by enhancing MHC class I tumor antigen processing." (PMID 33330025, 2020). "Our findings reveal that PSMB10 is not only overexpressed in KIRC tumor tissues but also has a profound negative impact on patient prognosis." (PMID 38794205, 2024). "Eight co-expressed genes (PSMB8, PSMB9, PSMB10, PSME2, TAP1, IRF1, FBOX6, ETV7) were identified as CD8+ T cell-related genes that promoted infiltration of CD8+ T cells, and were enriched in the MHC class I tumor antigen presentation process." (PMID 33330025, 2020).
tumor (continued). "In the analysis of gene expression in whole proteasomes including PSMB5 (β5), PSMB8 (iβ5), PSMB7 (β2), PSMB10 (iβ2), PSMB6 (β1), and PSMB9 (iβ1), these genes alternated or showed only slight in their expression following silencing of PSMB5 or PSMB7 in three tumor cells." (PMID 29515784, 2018). "Importantly, we found HLA-B, HLA-E, and PSMB10 all related to antigen presentation to be enriched among down-regulated genes in tumours with high LEF-1 expression suggesting an adverse impact of Wnt/β-catenin pathway on tumour recognition by immune cells." (PMID 40130164, 2025).
cancer (21 papers, 2012 to 2025). A tumor composed of atypical neoplastic, often pleomorphic cells that invade other tissues. "PSMB8, PSMB9 and PSMB10 are part of the immunoproteasome complex, which is activated in response to interferon gamma signaling, and has been previously associated to cancer cell survival and progression." (PMID 38519482, 2024). "PSMB10 has been considered a risk factor for the regulation of viral response and epithelial cell differentiation, particularly during immunocompromised-induced conditions such as cancer." (PMID 36544093, 2022). "Recent studies in various cancer types have shown that overexpression of IP subunits (PSMB8, PSMB9, PSMB10) is associated with improved survival and better response to ICI therapies." (PMID 41222746, 2025). "PSMB10 had lower staining intensity in cancer tissue, while PSMB10 had higher staining intensity in normal tissue." (PMID 34220795, 2021). "Consequently, 721 potentially damaging variants were identified by both databases in 28/32 cancer types and in all PSM genes, except PSMB10 and PSMG1-4." (PMID 36123629, 2022). "PSMB10 overexpression has also been associated with angiotensin II and inflammation in numerous cancers although not previously reported for PC, as far as our literature search has extended." (PMID 36075907, 2022). "In comparison to other cancer types, STS showed high expression of PSMB5, PSMB6 and PSMB7, the subunits of the constitutive proteasome and low levels of PSMB8, PSMB9 and PSMB10, the subunits specific to immunoproteasomes." (PMID 32851475, 2021). "In this study, we first demonstrated the relationship among PSMB8, PSMB9, PSMB10, PSME1, PSME2, and IRF1 in the immune micro-environment and immune score through TCGA whole cancer cohorts, and further, we proved the correlation between PSMB8, PSMB9, PSMB10, PSME1, PSME2, IRF1, and immune cells." (PMID 36700205, 2022). "Based on transcriptomic analyses of thousands of samples from The Cancer Genome Atlas, we report that expression of constitutive proteasome (CP) genes (PSMB5, PSMB6, PSMB7) and immunoproteasome (IP) genes (PSMB8, PSMB9, PSMB10) is increased in most cancer types." (PMID 27659694, 2016).
infection (15 papers, 2007 to 2025). The state of being infected such as from the introduction of a foreign agent such as serum, vaccine, antigenic substance or organism. "In response to inflammation or infection, proteolytic subunits of constitutive proteasome are replaced by immunoproteasome subunits Psmb8, Psmb9 and Psmb10 that are more efficient in processing endocytosed antigens for subsequent MHC I-restricted cross-presentation." (PMID 36993973, 2023). "Whether and how the simultaneous absence of the inducible catalytic subunits β1i/LMP2 (Psmb8), β2i/MECL-1 (Psmb9) and β5i/LMP7 (Psmb10) alters the course of infections remains unclarified." (PMID 33968021, 2021). "From the results of three independent experiments, we found that the inability to undergo autophagy during infection led to higher expression of many pro-inflammatory genes as compared to autophagy-competent cells, including established ISGs, such as Psmb10, Cd274, Cxcl10, Irf1 and Tap1." (PMID 29748576, 2018). "Except for PSMB2 and PSMB10, all other PSMBs were upregulated after influenza A virus (IAV, PR8 strain) infection of THP-1 cells." (PMID 30682859, 2019). "In line with IFNs being required for ImP induction, PSMB8 and 9 were not induced by wtVSV infection, and while the signal for PSMB10 was slightly increased by wtVSV, the expression remained lower compared to oVSV." (PMID 40872920, 2025). "We observed a large increase in both immunoproteasomal subunits PSMB8 and PSMB10, and the IFN-activated proteins ISG15 and MX1 in serum and in infected cells 3 and 7 days after infection, thus connecting these changes in blood proteins to those after SARS-CoV-2 infection." (PMID 37739942, 2023). "HiRIEF LC-MS/MS detected alterations in the remaining proteins, i.e., ISG20, PSMB8, PSMB10, ALDOC, and SERPINB1, emphasising the method’s ability to capture alterations deriving from infection that are not picked up by other methods." (PMID 37739942, 2023).
PSMB10 also shares sentences with these, for which no sentence is quoted: atrial fibrillation (3 papers); retinopathy (3); Autoimmunity (2); cardiac hypertrophy (2); hepatocellular carcinoma (2); lung adenocarcinoma (2); primary immunodeficiency (2); thyroid carcinoma (2); acute myeloid leukemia (1); alopecia (1); Anonychia (1); atherosclerosis (1); autoimmune myocarditis (1); autoinflammatory syndrome (1); breast invasive carcinoma (1); cardiomyopathy (1); cardiovascular diseases (1); cerebral toxoplasmosis (1); Charcot-Marie-Tooth disease (1); chronic myelogenous leukemia (1); clear renal cell carcinoma (1); colitis (1); Crohn disease (1); dermatomyositis (1); Diarrhea (1); ectodermal dysplasia (1); experimental autoimmune encephalomyelitis (1); fibrosis (1); Fundus dystrophy (1); head and neck squamous cell carcinoma (1).
A further 34 diseases each share a sentence with PSMB10 in 1 paper.